LINC01615 (long independently transcribed non-coding RNA 1615)
Synonyms: RP11-417E7.1; LINC02544
Gene: Long non-coding RNA gene on chromosome 6 (169,157,162 to 169,182,878, reverse strand). Ensembl gene ENSG00000223485.
Diseases named in the same sentence as LINC01615 in open-access papers:
LINC01615 is named in the same sentence as 16 diseases in open-access papers, as found by Europe PMC text mining. Sharing a sentence is not in itself a finding about the gene and the disease. The quoted sentences say what the papers report.
colorectal cancer (3 papers, 2022 to 2025). A primary or metastatic malignant neoplasm that affects the colon or rectum. "LINC01615 maintains cell survival under nutrient starvation by modulating the pentose phosphate pathway and regulates chemosensitivity in colorectal cancer." (PMID 40302795, 2025). "LINC01615 maintains cell survival in adaptation to nutrient starvation through the pentose phosphate pathway and modulates chemosensitivity in colorectal cancer." (PMID 37791141, 2023). "LINC01615 functions as an oncogene and is involved in cell proliferation, apoptosis, invasion, and migration in colorectal cancer cells." (PMID 35794984, 2022).
hepatocellular carcinoma (3 papers, 2022). A malignant tumor that arises from hepatocytes. "LINC01615 has also been identified to be associated with the extracellular matrix and had further impacts on the metastasis of hepatocellular carcinoma." (PMID 35350243, 2022). "Previous studies have shown that LINC01615 promotes tumorigenesis and progression in hepatocellular carcinoma, colon cancer, and clear cell renal cell carcinoma." (PMID 36230738, 2022).
breast carcinoma (2 papers, 2022 to 2023). "Moreover, the expression of LINC01615 is elevated in breast cancer patients, and overexpressed LINC01615 was associated with a poor prognosis." (PMID 36230738, 2022). "Only LINC01615 was significantly correlated with the survival prognosis of breast cancer patients, and the prognosis of patients with upregulated LINC01615 expression was significantly lower than that with low LINC01615 expression." (PMID 36230738, 2022). "Our research clarified that LINC01615 can act as an oncogenic factor in promoting the development of breast cancer." (PMID 36230738, 2022). "In vivo and in vitro experiments, we clarified that overexpression of LINC01615 can promote breast cancer cell metastasis ability." (PMID 36230738, 2022). "LINC01615 can potentially become a target molecule in the cancer metastasis therapy of breast cancer patients." (PMID 36230738, 2022). "We revealed that LINC01615 is regulated by the transcription factor SIPA1 in promoting breast cancer cell malignancy." (PMID 36230738, 2022). "This further indicates that LINC01615 can promote breast cancer cell migration and invasion." (PMID 36230738, 2022). "The results reveal a new mechanism that SIPA1 regulates breast cancer cell EMT and then promotes metastasis by up-regulating the expression of LINC01615, which provides a new way to clarify the process of metastasis in cancer." (PMID 36230738, 2022). "The expression of LINC01615 is regulated by the transcriptional activator SIPA1, thereby promoting carcinogenesis in breast cancer cells." (PMID 36230738, 2022).
gastric cancer (2 papers, 2022). A primary or metastatic malignant neoplasm involving the stomach. "Interestingly, LINC01615 may be a lncRNA associated with ferroptosis, and in gastric cancer cell lines, most LINC01615 is enriched in the cytoplasm." (PMID 35794984, 2022). "We also expected to provide a promising target for LINC01615 for research in the future, which was highly expressed in gastric cancer and cell lines and acted as a ceRNA to get involved in ferroptosis." (PMID 35242169, 2022). "LINC01615 is highly expressed in gastric cancer cell lines and tissues." (PMID 35242169, 2022). "We observed that in gastric cancer cell lines, most LINC01615 was enriched in the cytoplasm." (PMID 35242169, 2022).
head and neck squamous cell carcinoma (2 papers, 2022). A squamous cell carcinoma that arises from any of the following anatomic sites: lip and oral cavity, nasal cavity, paranasal sinuses, pharynx, larynx, and salivary glands. "Functionally, we validated that LINC01615 plays a pivotal role in head and neck squamous cell carcinoma cell proliferation, invasion, and migration." (PMID 35794984, 2022). "Functionally, we furtherly validated that LINC01615 plays a pivotal role in head and neck squamous cell carcinoma cell proliferation, invasion, and migration." (PMID 35794984, 2022). "To validate the function of LINC01615 on the biological behavior of head and neck squamous cell carcinoma, we transfected two independent siRNAs targeting LINC01615 in laryngeal squamous cell carcinoma cells HEP-2 and TU212." (PMID 35794984, 2022). "In addition, UALCAN program analysis also showed that the expression of LINC01615 in diverse cancer types such as bladder carcinoma (BLCA), head and neck squamous cell carcinoma (HNSC), and sarcoma (SARC) was notably upregulated." (PMID 35242169, 2022).
mesenchymal tumors (1 paper, 2022). "Also, the expression of Linc01615 was high in mesenchymal tumors (PAAD, GBM, SARC, and KIRC) and lowered in epithelial tumors (THCA, KICH, PRAD, and except BLCA)." (PMID 36120580, 2022).
triple-negative breast carcinoma (1 paper, 2022). An invasive breast carcinoma which is negative for expression of estrogen receptor (ER), progesterone receptor (PR), and human epidermal growth factor receptor 2 (HER2). "In conclusion, our study found that the up-regulation of SIPA1 can promote the expression of LINC01615, and the up-regulation of LINC01615 can promote the expression of MMP9 to promote the migration and invasion of triple-negative breast cancer." (PMID 36230738, 2022).
cancer (6 papers, 2022 to 2025). A tumor composed of atypical neoplastic, often pleomorphic cells that invade other tissues. "Even in mixed-class cancers, Linc01615 showed significantly higher expression than corresponding normal." (PMID 36120580, 2022). "We identified Linc01615 as a mesenchymal LncRNA whose expression significantly correlated with survival in several cancer types." (PMID 36120580, 2022). "To understand the role of Linc01615 in cancer cells, we identified the MDAMB231 and 143B cells with high expression of Linc01615." (PMID 36120580, 2022). "Considering the LINC01615 expression results in the activation of different pathways, we explored the genomic heterogeneity (MSI, HRD, and TMB) based on the LINC01615 expression in the pan-cancer level." (PMID 35794984, 2022).
tumor (3 papers, 2022). "We found that the decreased tumor volume caused by SIPA1 knockdown was offset by overexpression of LINC01615." (PMID 36230738, 2022). "The differences in LINC01615 expression levels in different tumor types may reflect different underlying functions and mechanisms." (PMID 35794984, 2022). "The results showed that the expression level of LINC01615 in tumor tissues was higher than that in normal breast tissues." (PMID 36230738, 2022).
LINC01615 also shares sentences with these, for which no sentence is quoted: lymph node metastasis (2 papers); bladder carcinoma (1); clear cell renal cell carcinoma (1); colon cancer (1); laryngeal squamous cell carcinoma (1); lung squamous cell carcinoma (1); sarcoma (1).